MTAP (methylthioadenosine phosphorylase)
Diseases named in the same sentence as MTAP in open-access papers (continued):
Sharing a sentence is not in itself a finding about the gene and the disease.
meningioma (8 papers, 2020 to 2025). A generally slow growing tumor attached to the dura mater. "In 2002, deletions in chromosome 9p21, which includes the CDKN2A, CDKN2B and MTAP genes, were linked to malignant progression or anaplastic phenotype in meningiomas." (PMID 40227557, 2025). "Forty-two (42/43) tumors showed expression of MTAP at the 1:200 dilution, with one meningioma showing loss of MTAP expression (#47) and two cases showing focal expression (#19 and #30)." (PMID 39409918, 2024). "Recently, it has been suggested that MTAP expression by IHC can be utilized as a surrogate marker for CDKN2A/B loss in meningiomas." (PMID 39409918, 2024). "One grade 3 meningioma that demonstrated homozygous CDKN2A loss by FISH also showed loss of MTAP expression by IHC." (PMID 39409918, 2024). "MTAP immunohistochemistry has been described as a surrogate marker for homozygous CDKN2A loss correlating with higher graded meningiomas." (PMID 38023177, 2023). "Furthermore, it has been demonstrated that meningiomas with homozygous CDKN2A/B deletions frequently harbor the loss of the methylthioadenosine phosphorylase (MTAP), which is in close proximity of the gene loci." (PMID 38017560, 2023). "This discrepancy can result in the missing of CDKN2A homozygous deletions and misgrading of meningiomas when MTAP IHC is used as a sole surrogate marker or when an inappropriate FISH probe is employed." (PMID 40227557, 2025). "This study suggests that IHC for MTAP is a promising, cost-effective method for identifying high-grade meningiomas, offering a quicker and less expensive alternative to existing techniques." (PMID 39409918, 2024). "MTAP immunostaining can be a good surrogate marker for identifying CDKN2A homozygous deletion in meningiomas." (PMID 39409918, 2024). "In this study, we evaluate the utility of evaluating p16 and MTAP expression by IHC as surrogate markers for homozygous deletion of CDKN2A/B in meningiomas." (PMID 39409918, 2024). "Our results with p16 expression in meningiomas show limited correlation with CDKN2A status, suggesting that MTAP immunostaining is superior to p16 for the evaluation of CDKN2A/B deletion in meningiomas." (PMID 39409918, 2024). "In our study, at institution 1 there were two meningiomas with focal MTAP expression at the 1:200 dilution (one grade 1 and two grade 2 meningiomas)." (PMID 39409918, 2024). "One grade 2 meningioma showed regional CDKN2A loss by FISH and variable MTAP expression under different IHC conditions." (PMID 39409918, 2024). "The grade 2 meningioma (#30) maintained focal MTAP expression even at the higher antibody concentration (1:100)." (PMID 39409918, 2024). "However, additional studies are needed to confirm the utility of MTAP expression for the diagnosis and grading of meningiomas." (PMID 39409918, 2024). "MTAP IHC is a promising surrogate marker for the evaluation of CDKN2A status in meningiomas." (PMID 39409918, 2024). "Focal MTAP expression meningiomas can be assessed with CDKN2A FISH to determine true CDKN2A status." (PMID 39409918, 2024). "The hypothesis of this study is that MTAP and p16 expression as assessed by IHC can act as reliable surrogate markers for detecting homozygous CDKN2A/B loss in meningiomas, providing a cost-effective alternative to more expensive and less accessible molecular techniques." (PMID 39409918, 2024). "In our study, MTAP expression showed 100% (41/41) specificity at the 1:100 dilution and 95% (39/41) specificity at the 1:1200 dilution for identifying meningiomas with intact CDKN2A status and 100% (2/2) sensitivity for detecting meningiomas with CDKN2A homozygous loss." (PMID 39409918, 2024). "We identified anaplastic meningiomas with homozygous CDKN2A deletions but retained MTAP gene and MTAP protein expression." (PMID 40227557, 2025). "In a large study involving 50 meningiomas, including eight WHO grade 3 cases, MTAP IHC demonstrated strong correlation with FISH results and outperformed p16 IHC." (PMID 40227557, 2025).
meningioma (continued). "The grade 1 meningioma (#19), which showed intact CDKN2A status by FISH, showed expression of MTAP when the antibody concentration was increased to a 1:100 dilution." (PMID 39409918, 2024). "In this study, we investigated the utility of MTAP and p16 IHC as surrogate markers of CDKN2A deletion in meningiomas." (PMID 39409918, 2024). "Molecular analyses in higher-grade meningiomas should then be performed on tumor regions showing no immunohistochemical staining for p16/MTAP." (PMID 40227557, 2025). "In this study, we demonstrate that in meningiomas, CDKN2A copy number status may differ from the MTAP status." (PMID 40227557, 2025). "Grade-wise comparisons on MGI (benign) vs MGII (atypical) meningiomas revealed prominent involvement of TIMM50, SEC23A, MTAP, RPS23, and ADRM1 based on the concordance analysis of highly ranked features from across 20 Machine Learning randomized iterations obtained via the methods of the Ball group." (PMID 32974197, 2020). "Although MTAP staining offers the benefit of labeling normal cells as an internal (positive) control, our work shows that it is not always a dependable surrogate marker for CDKN2A status, particularly in anaplastic meningiomas with differing CDKN2A and MTAP statuses." (PMID 40227557, 2025). "In our study, even though institution 1 showed high sensitivity and specificity for p16, given the inconsistency between the institutions and the high amount of faint positive staining, p16 alone might not be as good as MTAP for determining CDKN2A/B status in meningiomas." (PMID 39409918, 2024). "MTAP immunohistochemistry has been demonstrated to be a surrogate marker for homozygous CDKN2A/B deletions and might highlight patients potentially benefiting from novel therapies inhibiting the promotion of DNA damages and mitotic dysfunction in meningioma cells." (PMID 38017560, 2023). "We conclude that negative p16/MTAP IHC in high-grade meningiomas should prompt molecular analysis for CDKN2A deletions, and MTAP IHC should not be solely relied upon for classification." (PMID 40227557, 2025).
nevus (8 papers, 2013 to 2026). Nevus (or naevus, plural nevi or naevi, from nævus, Latin for "birthmark") is the medical term for sharply circumscribed[1] and chronic lesions of the skin or mucosa. "The analysis confirmed previously established nevus-associated loci (MTAP, PLA2G6, IRF4) and uncovered novel associations with single-nucleotide polymorphisms (SNPs) in KITLG and a region on chromosome 9q32." (PMID 41596618, 2026).
pancreatic adenocarcinoma (7 papers, 2018 to 2026). "Our findings also suggest a considerable diagnostic utility of MTAP IHC for the detection of pancreatic adenocarcinoma, especially in the case of low-grade cancer and in small biopsies." (PMID 40227771, 2025). "MTAP deficiency in pancreatic adenocarcinoma appears to be a suitable target of new therapies and trial approaches under development." (PMID 40227771, 2025). "Pancreatic adenocarcinomas may thus represent an ideal cancer type for studying new drugs targeting MTAP-deficient cancer cells in clinical trials." (PMID 40227771, 2025). "Considering also their aggressive clinical behavior, pancreatic adenocarcinomas may represent an ideal cancer type for studying new drugs targeting MTAP-deficient cancer cells in clinical trials." (PMID 40227771, 2025). "Due to the aggressive clinical behavior of pancreatic adenocarcinomas, this tumor type may represent an ideal cancer type for clinical trials studying new drugs targeting MTAP-deficient cancer cells." (PMID 40227771, 2025). "The additional whole-section evaluation of 19 consecutive cases led to the identification of one pancreatic adenocarcinoma with heterogeneous MTAP deficiency, while 4 cases showed a homogeneous MTAP deficiency, and 14 cases homogeneously retained MTAP expression." (PMID 40227771, 2025). "The somewhat lower rates of MTAP deficiency in NGS studies may be due to the notoriously low tumor cell density in pancreatic adenocarcinomas, which are characterized by a dense desmoplastic stroma and large distances between invasively growing tumor cell glands." (PMID 40227771, 2025). "MTAP deficiency and the level of MTAP expression were both unrelated to pT, pN, grade, tumor size, and resection margin status in our 478 interpretable primary pancreatic adenocarcinomas and unrelated to overall survival in a subset of 64 primary pancreatic adenocarcinomas." (PMID 40227771, 2025). "The successful comparative analysis of 423 primary pancreatic adenocarcinoma samples by FISH and IHC on consecutive sections demonstrated a high precision of MTAP IHC for the detection of cases with a homozygous MTAP deletion." (PMID 40227771, 2025).
breast tumors (6 papers, 2014 to 2023). "In MTAP-deficient breast tumor cells, selective ODC inhibitor difluoromethylornithine (DFMO) could exert metastasis-promoting effect." (PMID 37091983, 2023). "Relative mRNA MTAP expression value was 1.39 ± 0.75 and 1.98 ± 1.05 in fresh primary breast tumors and normal samples, respectively." (PMID 26751376, 2016). "In a previous study, we found a high rate (90%) of concordant LOH between CDKN2A and MTAP genes in primary breast tumors." (PMID 26751376, 2016). "Curtis and colleagues discovered a high frequency of MTAP deletions in an integrated analysis of copy number and gene expression with two sets of almost a thousand primary breast tumors." (PMID 26751376, 2016). "Conversely, additional putrescine could impair the aggressive phenotypes of MTAP-overexpressing breast tumor cells." (PMID 37091983, 2023). "Notably, we found that primary breast tumors from MTAP knockdown group showed typical curvilinear tumor vessels, and hence we detected the angiogenesis in tumor tissues by CD31 immunostaining." (PMID 35541910, 2022). "MTAP was found significantly less expressed in TNBC than in Luminal-A breast tumors." (PMID 26751376, 2016). "This suggests that a lack of MTAP expression is associated with more aggressive breast tumors and may support the development of new therapeutic approaches based on MTAP status in TNBC." (PMID 36913304, 2023). "In our study, we also confirmed that the mRNA expression levels of MMP2 was significantly upregulated in MTAP-knockdown BT20 cells but downregulated after ODC inhibitor DFMO treatment, indicating MTAP could block breast tumor angiogenesis via inhibiting the ODC-MMP2 signaling axis." (PMID 35541910, 2022). "Our study also elucidated that MTAP involves in the polyamine biosynthesis by regulating ODC activity, thereby suppressing breast tumor metastasis." (PMID 35541910, 2022). "Although the difference in MTAP expression between fresh tumors and normal tissue was not statistically significant, MTAP expression was significantly higher in Luminal-A breast tumors compared to TNBC." (PMID 36913304, 2023). "Here, we assessed MTAP mRNA expression in a sample of fresh breast tumors and normal breast tissue, and the difference was not statistically significant." (PMID 26751376, 2016). "However, MTAP expression was significantly higher in Luminal-A breast tumors than in TNBC, suggesting the lack of expression in more aggressive breast tumors and the possibility of using the new approaches based on MTAP status in TNBC." (PMID 26751376, 2016).
urothelial carcinoma (6 papers, 2018 to 2026). A malignant neoplasm derived from the transitional epithelium of the urinary tract (urinary bladder, ureter, urethra, or renal pelvis). "In summary, the results of our study show that complete MTAP expression loss occurs in 20–30% of urothelial carcinomas and that MTAP expression loss is restricted to neoplastic urothelium carrying homozygous 9p21 (MTAP) deletions." (PMID 39668577, 2025). "In noninvasive urothelial carcinomas, MTAP expression loss was more common in pTaG2 high‐grade (30.7%) than in pTaG2 low‐grade (10.8%) or pTaG3 carcinomas (17.9%; p < 0.0001)." (PMID 39668577, 2025). "MTAP expression loss was more common in muscle‐invasive urothelial carcinomas (pT2–4, 26.8%) than in pTaG3 carcinomas (17.9%; p = 0.0345)." (PMID 39668577, 2025). "All together these data suggest considerable utility of drugs targeting MTAP deficiency in advanced urothelial carcinoma." (PMID 40664803, 2025). "The results of this study identified 33–39% of our muscle-invasive urothelial carcinomas of the urinary bladder as MTAP deficient." (PMID 40664803, 2025). "The enzyme S‐methyl‐5′‐thioadenosine phosphorylase (MTAP) is of topical interest as an indirect drug target as well as a predictive and diagnostic marker in urothelial carcinoma." (PMID 39668577, 2025). "In a recent study on 1,792 analyzable muscle-invasive urothelial carcinomas, we found MTAP deficiency in 24.0% of cases and observed a sensitivity of 98.4% and a specificity of 99.6% for MTAP IHC to detect homozygous 9p21 deletions." (PMID 40664803, 2025). "In this study, we aimed to understand the prevalence of MTAP deficiency in urothelial carcinoma, and to determine its relationship with parameters of the immune microenvironment, clinicopathological parameters, and disease outcome." (PMID 39668577, 2025). "Most recently a partial response was reported in 3 and a complete response in one out of 10 MTAP deficient urothelial carcinomas that were previously treated by multiple lines of chemotherapy after single agent treatment by the MAT2A inhibitor IDE39712." (PMID 40664803, 2025). "Urothelial carcinoma is another tumor entity with a high rate of 9p21 deletions, which could be treated by drugs targeting MTAP deficiency." (PMID 39668577, 2025). "MTAP deficiency is mostly homogeneous in advanced urothelial carcinoma." (PMID 40664803, 2025). "The significantly lower rate of PD‐L1‐positive tumor cells and macrophages, as well as of intratumoral CD8‐positive and CD4‐positive lymphocytes, M2 macrophages, and dendritic cells in MTAP‐deficient urothelial carcinomas is consistent with more efficient immune evasion in these tumors." (PMID 39668577, 2025). "Advanced urothelial carcinoma may thus represent an ideal cancer type for new drugs targeting MTAP deficient cancer cells." (PMID 40664803, 2025). "In urothelial carcinoma, MTAP expression was considered strong in 12.8%, moderate in 32.9%, and weak in 30.3% while it was completely absent in 24.0% of cases." (PMID 39668577, 2025). "A total of 1,792 (72.7%) of 2,466 urothelial carcinomas were interpretable for MTAP IHC and 1,711 of 2,710 (63.1%) were evaluable for 9p21 deletion assessment by FISH." (PMID 39668577, 2025). "While other mechanisms such as promoter methylation may contribute to MTAP expression loss in rare cases, our data demonstrate that biallelic genomic loss is the major (and probably only) mechanism that can cause complete MTAP deficiency in urothelial carcinoma." (PMID 39668577, 2025). "Approximately 30 patients with MTAP-delated urothelial carcinoma will be enrolled in this phase I dose-escalation study and 50 patients in the dose-expansion trial." (PMID 41465382, 2025).
urothelial carcinoma (continued). "Considering that urothelial carcinomas are often treated by CPIs and that considerable diagnostic difficulties exist in the diagnosis of low‐grade neoplasms/flat dysplasia and in urine cytology, immunohistochemical MTAP analysis could also be of diagnostic and predictive value in this tumor type." (PMID 39668577, 2025). "Also of interest, both MTAP deficiency and CDKN2A loss could be linked to poor response to immune checkpoint inhibitors (CPIs) in urothelial carcinoma." (PMID 39668577, 2025).
atherosclerosis (5 papers, 2011 to 2025). A disease characterized by the build-up of fatty material and calcium deposition in the arterial wall resulting in partial or complete occlusion of the arterial lumen. "Together, the transcriptional programs activated by MTAP perturbation in primary vascular fibroblasts closely mirror those observed in pathological vascular remodeling, including atherosclerosis, aneurism, and peripheral artery Disease (PAD)." (PMID 41332607, 2025). "These signatures overlap with those observed in atherosclerosis, aortic aneurysm, and peripheral artery disease, indicating that reduced MTAP expression may promote a pro-atherogenic cellular phenotype." (PMID 41332607, 2025). "The expression of ANRIL transcripts (EU741058 and NR_003529) in atherosclerotic plaque tissue was directly correlated with severity of atherosclerosis; however, no such correlation was found in CDKN2A, CDKN2B and MTAP." (PMID 21698238, 2011).
colon carcinoma (5 papers, 2021 to 2025). "In preclinical studies, AZ-PRMT5i-1 demonstrated significant antiproliferative activity in MTAP-deficient HCT-116 colon cancer cells." (PMID 39826691, 2025). "In preclinical tests, MRTX1719 showed robust antiproliferative activity in MTAP-deleted HCT116 colon cancer cells, with an IC50 of 8 nM, compared to an IC50 of 653 nM in WT HCT116 cells, highlighting its over 70-fold selectivity for MTAP-deficient cells." (PMID 39826691, 2025). "Cells from an MTAP-deleted colon carcinoma cell line displayed reduced PRMT5 methylation activity and increased sensitivity to PRMT5 depletion." (PMID 34573422, 2021). "Recent publications have demonstrated an SL role for RIOK1 in methylthioadenosine phosphorylase (MTAP)-depleted cells and its overexpression in colon cancer cells was shown to promote cell proliferation in vitro in human CRC." (PMID 37298928, 2023). "Therefore, the elevated MTA concentrations observed as a consequence of MTAP inhibition with MTDIA are proposed to be a key component contributing to reduced cancer growth, a feature shown to be disruptive to colon cancer cells." (PMID 33893330, 2021).
T-cell acute lymphoblastic leukemia (5 papers, 2009 to 2025). Acute lymphoblastic leukemia of T-cell origin. "Although there have been no reports of single pralatrexate use for MTAP-null tumors, it has been shown to be effective on MTAP-deficient T-cell acute lymphoblastic leukemia (T-cell ALL) when used in combination with 6-thioguanine." (PMID 41439984, 2025). "Results of the combination of PDX, 6-TG and leucovorin against CEM xenografts show promise as an effective therapy for MTAP-deficient T-cell ALL." (PMID 25917288, 2015). "Given that a high percentage of pediatric patients with T-cell ALL lack MTAP, this may be the explanation for the clinical benefit observed with MTX." (PMID 25917288, 2015). "Studies have shown that around 70 % of T-cell ALL cases have MTAP deletions." (PMID 25917288, 2015).